EGFR (epidermal growth factor receptor)
Diseases named in the same sentence as EGFR in open-access papers (continued):
Sharing a sentence is not in itself a finding about the gene and the disease.
cancer (continued). "Moreover, molecular modeling studies using PyRx revealed that 4a, among all SOXs, was found to be the best inhibitor of distinct biomarkers associated with cancer progression, i.e., human CD-44, EGFR, AKR1D1, and HER-2." (PMID 37108498, 2023). "However, it was three decades ago when the discovery of EGFR mutations and overexpression in cancer cells increased its clinical value, opening the gate to therapies targeting it precisely." (PMID 37232831, 2023). "By now, most EGFR-TKIs aim to target the biological functions of EGFR caused by kinase activation, and to induce cytotoxicity of cancer cells, yet drug-resistant mutations, together with changes in the stability of EGFR still limits the use and efficacy of EGFR-TKIs in clinical practice." (PMID 36910653, 2023). "The epidermal growth factor receptor (EGFR) is associated with a variety of molecules and pathways involved in cell proliferation, and it is widely utilized as a pathological diagnostic marker for many types of cancer." (PMID 37208730, 2023). "Careful analysis of individual patient characteristics and the multitude of variables associated with cancer treatment may establish a more concrete explanation of the role of EGFR and VTE." (PMID 37232831, 2023). "Many oncogenic mutations on EGFR have been identified in cancer cells." (PMID 36739948, 2023). "A validation set using CD8+ T cell immunochemical staining demonstrated an immune profile similar to the previous two data sets for EGFR rare mutations, and a better prognosis for these cancer types than L858R and exon 19 deletions, with PD-1/PD-L1 inhibitor treatment." (PMID 37033978, 2023). "Importantly, inhibition of IGF1R completely eliminates the ability of EGFR-mutated cancer cells to generate DTPs." (PMID 37894376, 2023). "Furthermore, the in silico investigations for the identification of its probable mechanism of anti-cancer action revealed that these compounds showed good binding affinities and stable associations with the EGFR, PI3K, mTOR, and Tubulin polymerzation enzymes." (PMID 36769327, 2023). "While essential for the development and maintenance of normal epithelial tissue, changes to EGFR biology including overexpression/amplification, mutation, and altered trafficking, allow aberrant signaling and functions leading to cancer and other diseases." (PMID 37720348, 2023). "Exosomes can be internalized by EGFR-mutated cancer cells through lattice-protein-dependent endocytosis, and then encapsulated exosomal wild-type EGFR protein then activates the downstream PI3K/AKT and MAPK signaling pathways and triggers osimertinib resistance." (PMID 37089959, 2023). "Environmental chemicals such as PM2.5 can also activate EGFR and become a risk factor for cancer." (PMID 37722877, 2023). "Interestingly, EGFR inhibitors have been identified to have an anti-cancer effect in cancer cells carrying BRAF mutation." (PMID 36658200, 2023). "Thus, EGFR mutation status showed an overall discordance rate of 15.4% (Wilcoxon signed ranks test, P = 0.461) between the primary cancer and the corresponding BMs." (PMID 35912248, 2022). "A total of 159 patients with baseline EGFR exon 21 L858R mutated NSCLC met the study’s inclusion criteria were enrolled in the study at our center (Cancer center, Sir Run Run Shaw Hospital, Zhejiang University School of Medicine, Hangzhou, China) between Jan 1, 2015, to Jan 1, 2021." (PMID 36028744, 2022). "Dysregulation of the ERBB/EGFR signalling pathway causes multiple types of cancer." (PMID 35971826, 2022).
cancer (continued). "Several studies have also shown that the EGFR status is associated with drug resistance in cancer, which suggests that EGFR knockout RC21 cells could be a cisplatin-resistant cell model." (PMID 35619895, 2022). "EGFR mutations, amplifications or in-frame deletions can occur in regions corresponding to the extracellular or intracellular portions of the protein and are quite specific to different cancer types." (PMID 35053553, 2022). "Together, thesedata suggest that the detection of a hydrophilic transmembrane mutationin EGFR in a cancer sample might be a first hint toward activatedEGFR signaling, although this will certainly not be true for all hydrophilictransmembrane mutations." (PMID 36148499, 2022). "This retrospective review of NSCLC genomics data from the BC Cancer Genomic Lab Oncopanel Dataset summarizes the frequency of actionable driver mutations (EGFR, KRAS G12C, MET Exon 14 skip, ALK fusion, and ROS1 fusion), PDL-1 expression, and treatment wait times among five health authorities." (PMID 36661661, 2022). "Moreover, the PI3K-Akt signaling pathway downstream of EGFR, activated in drug-resistant cancer cells with loss of EGFR driver gene mutation, was highly expressed in post-treatment tumors." (PMID 36505794, 2022). "PL retained driver EGFR mutation and other cancer associated genes after neoadjuvant immunotherapy." (PMID 36123526, 2022). "Additionally, the frequency of EGFR mutations was high in cancers occurring in the upper portion of the lung (right upper lobe, right middle lobe, or left upper lobe) (p = 0.002)." (PMID 35740676, 2022). "Nevertheless, the frequency of EGFR mutations in cancer patients is ambiguous." (PMID 36447228, 2022). "However, the role of exosomes and membrane-associated receptors, particularly EGFR as mediators of cell proliferation and invasion in cancer progression remains unexplored." (PMID 36114463, 2022). "Reduced EGFR TK activity in response to TKIs might impair DNA replication and repair processes and boost the production of mutations for cancer progression." (PMID 34319535, 2022). "Moreover, EGFR mutations are suggestively associated with disease-specific and progression-free survival in H&N cancers." (PMID 35409179, 2022). "Given that EGFR activates signalling networks associated with promoting cell survival, growth, invasion and proliferation, it is unsurprising that aberrations that result in hyperactivation of EGFR are common in many cancers." (PMID 35053553, 2022). "Three of these have been directly linked to apoptosis: miR-4767 in vascular epithelial cells through targeting BCL2L12 and EGFR, miR-3202 which was shown to cause apoptosis in endothelial cells, and miR-384 has been linked to inducing apoptosis in certain types of cancers." (PMID 35468884, 2022). "Furthermore, SET/CIP2A overexpression was frequently observed in cancers with mutations in various oncogenes (e.g., EGFR, KRAS, NRAS, and BRAF)." (PMID 36463234, 2022). "This study aimed to examine the diverse EGFR mutation statuses in multifocal cancer lesions." (PMID 35740676, 2022). "Mutations in oncogenes such as KRAS and EGFR cause a high proportion oflung cancers." (PMID 35930804, 2022). "Increased levels of EGFR expression or increased gain-of-function due to gene amplification, duplication, mutations, deletions, or in-frame alteration is frequent in several human cancers and is associated with an adverse prognosis." (PMID 35213974, 2022). "However, the role of deregulated EGFR signaling in cancer development is more complex than merely causing excess cell proliferation." (PMID 34982813, 2022).
cancer (continued). "From January 2011 to May 2020, patients with stage II–III EGFR-mutated adenocarcinoma who underwent cancer resection surgery at a single center were enrolled." (PMID 35360423, 2022). "The response to TKIs in a subset of patients with NSCLC, whose tumors express EGFR carrying activating mutations, has been excellent but short-lived due to the inevitable evolution of cancer cells to acquire secondary resistance mutations, preventing the binding of TKIs to EGFR." (PMID 36185288, 2022). "Additionally, the SPINK1 gene has been identified to be associated with many types of cancer, which is mostly attributed to potential epidermal growth factor receptor (EGFR) binding." (PMID 35408828, 2022). "EGFR-mut cancers have fewer average mutations than KRAS-mut and NEK." (PMID 36612014, 2022). "Based on our previous studies and current findings and others, we hypothesized that when possessing a constitutive activating EGFR signaling due to activating mutation, the cancer cells may reduce its dependence on ERs signaling." (PMID 35664735, 2022). "Gefitinib, one of the widely used EGFR-TKIs, has been approved for the first-line treatment of NSCLC with sensitizing EGFR mutations (exon 19 deletion or L858R point mutation), while drug resistance in cancer cells contributes to the limited clinical efficacy of the targeted drug." (PMID 35677158, 2022). "In this context, CS-lipid NPs were designed to deliver anti-galectin-1 and anti-epidermal growth factor receptors-siRNAs in glioblastoma treatment because galectin-1 and EGFR are overexpressed in glioblastoma cells and are associated with the proliferation and invasion of cancer cells." (PMID 36358663, 2022). "Circ-EGFR encodes a novel EGFR variant termed rolling-translated EGFR (rtEGFR) which interacts with EGFR, maintains its membrane localization, and thus leads to enhanced downstream signaling and cancer progression." (PMID 36009578, 2022). "However, the vast majority of EGFR-associated cancer research has been focused on cancer cells per se, leaving the host-resident stroma largely overlooked." (PMID 36202915, 2022). "In particular, the EGFR variant III (EGFRvIII) is expressed in cancer cells." (PMID 35884906, 2022). "Gefitinib is a TKI that treats NSCLC patients whose cancers have particular EGFR mutations." (PMID 35402265, 2022). "In total, patients treated with neoadjuvant immunotherapy were preliminarily screened from 26 centers around China, and 40 NSCLC patients that were treated with neoadjuvant immunotherapy and harboring EGFR mutations were collected from 8 thoracic and cancer centers." (PMID 36123526, 2022). "In these assays, two different cancer genes, BRAF and EGFR, were examined by using WT and cancer mutant plasmid DNA templates [single nucleotide (BRAF V600E and EGFR L858R) as well as deletion/insertion (EGFR Ex19Del and EGFR Ex20Ins) variants] and primers specific to cancer mutations." (PMID 36058471, 2022). "EGFR activation in cancer is associated with cancer progression." (PMID 35705962, 2022). "Consequently, EGFR is also considered one of the first receptors to be identified as a prime target for cancer treatment associated with different types of solid tumors." (PMID 36654821, 2022). "EGFR (also known as ERBB1) is associated with cancer progression and its inhibition via monoclonal antibodies (such as cetuximab and panitumumab) or TKIs (such as erlotinib and gefitinib) has been the first strategy evaluated among growth factor receptors targeting therapies." (PMID 35497981, 2022). "Moreover, the positive predictive value of the integrated model for EGFR mutations was 0.917, which indicates that the ability of the integrative model to identify the EGFR mutation and nodules’ benefit from cancer genetic testing was strong." (PMID 36675677, 2022).
cancer (continued). "Aptamers for EGFR are widely developed for diagnostic strategies in related cancers." (PMID 36431072, 2022). "EGFR expression is associated with the progression of many types of cancer." (PMID 36012588, 2022). "Epidermal growth factor receptor (EGFR) mutations are among the most common oncogenic drivers in advanced or metastatic non-small cell lung cancer (aNSCLC), which continues to be the most common cause of cancer deaths in the world." (PMID 36551611, 2022). "Furthermore, ST6GAL1-mediated α2,6-linked sialylation has been implicated in activating PI3K/AKT, epidermal growth factor receptor (EGFR) in some cancers, and cell growth and proliferation." (PMID 35676533, 2022). "EGFR-mutated cancer cells have been shown to be sensitive to olaparib both in vivo and in vitro." (PMID 35702041, 2022). "In fact, more than 1000 distinct EGFR mutationsare listed in the Catalogue of Somatic Mutations in Cancer (COSMIC),but for most of them, the functional consequence is unknown." (PMID 36148499, 2022). "Several signaling pathways are associated with genetic mutations in cancer, including the upregulation of the Wnt pathway and growth factors such as EGFR leading to cancer growth, metastasis, cell proliferation, invasion, differentiation, angiogenesis, and apoptosis." (PMID 35744786, 2022). "EGFR is abnormally activated through various mechanisms (such as receptor overexpression, mutation, ligand-dependent receptor dimerization, ligand independent activation, etc.), which is related to the occurrence of various human cancers." (PMID 36189266, 2022). "In addition, the anti-proliferative potential of the most potent EGFRWT inhibitors was analysed towards two EGFR mutated cancer cell lines; NCI-H1650 and NCI-H1975." (PMID 36000167, 2022). "However, additional studies are needed to clarify the molecular mechanisms of GPE via EGFR signalling pathway underlying anti‐cancer activity in CMCs." (PMID 34882994, 2022). "We previously developed a bispecific RIT targeting the overexpressed EGFR and EGFRvIII variant on cancer cells, designated as DT390-HuBiscFv806 (hDT806), by fusing two humanized single-chain variable fragments (scFv) derived from monoclonal antibody mAb806 to the truncated form of DT." (PMID 35453686, 2022). "The EGFR pathway is associated with several cancer progressions, including NSCLC." (PMID 35402265, 2022). "Both pre-existing and de novo generation of genome wide mutations have been observed in vivo and in vitro, suggesting the EGFR TKIs initiate genomic instability to generate and select for mutations that confer resistance to their inhibition of cancer cell growth and induction of apoptosis." (PMID 34319535, 2022). "Of the remaining 333 cases, 201 had EGFR mutation-positive (EGFRm-positive) cancers." (PMID 35387120, 2022). "We speculate that the heterogeneity of mixed-lineage cancer cells may underlie variants in therapeutic responses to the EGFR-TKI target therapy between ADC and SCC patients." (PMID 35962452, 2022). "The understanding of genomic alterations in cancer, thanks to extensive collaborative work, have enabled the identification of possible diagnostic and therapeutic targets, one of which is the epidermal growth factor receptor (EGFR)." (PMID 35954442, 2022). "Analyses specifically examined associations between four visfatin single nucleotide polymorphisms (SNPs) rs11977021, rs61330082, rs2110385, and rs4730153, which have been studied for their association with risk of developing various cancers, EGFR status and clinicopathologic characteristics in LUAD." (PMID 36429891, 2022). "We also identified several metastasis-associated glycoproteins including MMP-14, EGFR, αV, β1, and β4 integrins that displayed higher levels of the GalNAc glycotope in lectin pull-down samples of highly invasive cancer cell lines, in contrast to poorly invasive cells." (PMID 35028012, 2022). "Recent studies have implicated EGFR as an important modulator of cancer metabolism." (PMID 35978801, 2022).
cancer (continued). "Overexpression and mutation of EGFR reflect cancer progression and prognosis." (PMID 35578244, 2022). "In this study, we assessed the biological effects of Q276P/R326Q polymorphisms on CD148's activity to suppress cancer cell proliferation and EGFR signaling by stably introducing wild‐type (WT) or mutated (Q276P/R326Q) CD148 to A431D epidermoid cancer cells that lack endogenous CD148 expression." (PMID 34791835, 2022). "We and others have shown that interactions with integrins and FN at the plasma membrane are essential to activating “outside-in” signaling (FAK, Akt, β-catenin, Src, epidermal growth factor receptor/EGFR) and are clearly implicated in cancer metastasis and stemness." (PMID 35681474, 2022). "One of the mechanisms leading to EGFR dysregulation in cancer is the occurrence of activating mutations in the TKD, hence we performed sequence analysis of a region of 1329 bp encompassing this domain (~34% of EGFR transcript) as the preliminary step of our experimental plan." (PMID 36467642, 2022). "However, the intrinsic and acquired resistance in primary and recurrent cancer which is mediated by EGFR mutations after target treatment leads to difficult therapeutic." (PMID 35840984, 2022). "However, deregulation of EGFR signaling through mutations, overexpression, or gene amplification commonly results in development and progression of several human cancers and resistance to therapies." (PMID 36575233, 2022). "Similarly, single-molecule quantification would be valuable to probe different carcinomas, for example, those of the lung in which EGFR mutations are implicated in cancer or in the design of cell surface logic gates for targeted therapies." (PMID 35612280, 2022). "Abnormal activation of downstream signals of EGFR is linked to cancer occurrence and progression." (PMID 35637973, 2022). "Thus, scFv selection is crucial, mAb806 binds to the EGFR287–302 epitope, which is exposed when EGFR overexpressed or when EGFR is mutated in cancer cells." (PMID 36551506, 2022). "Just like erlotinib, it is more effective in cancers with mutated and overactive EGFR." (PMID 35785151, 2022). "A recent study took advantage of mesoporous silica nanoparticles (MSNs) with EGFR-targeting aptamers; these nanoparticles interacted with circulating cancer-derived EGFR+ exosomes and eliminated these exosomes, causing their entry into the small intestine, which reduced the formation of metastasis." (PMID 35039054, 2022). "It has been demonstrated that cell-free DNA harbors cancer-associated mutations, and this combination has been harnessed for the detection of cancer-related mutations (EGFR-L858R and BRAFV600E) in cell-free DNA samples containing as little as 0.1% mutant alleles." (PMID 35163678, 2022). "Furthermore, anthocyanidin extracted from fruits and vegetables was identified as an effective inhibitor of EGFR mutated cancers, and a low-protein diet combined with an EGFR inhibitor was reported to be a promising cancer therapy method." (PMID 36530673, 2022). "TGFα-EGFR signaling is associated with carcinogenesis and cancer progression." (PMID 35290621, 2022). "Similarly, ANOs and TRP channels are also found in lipid rafts, often linked with receptor proteins such as EGFR as part of ion channel complexes in cancer cells, and function as a means of localising intracellular calcium signals." (PMID 36497413, 2022). "Additionally, as a crucial regulator of survival, cell cycle arrest, and apoptosis of cancer cells, the NF-κB signaling pathway has not only been linked to the oncogenic potential of the EGFR but is also involved in the acquisition of EGFR-TKIs resistance." (PMID 35049931, 2022). "Oncogenic alterations may result in EGFR overexpression as well, which eventually increases the cancer incidence risk via regulating related signaling pathway." (PMID 36619616, 2022).